FOXP3 (forkhead box P3)
Diseases named in the same sentence as FOXP3 in open-access papers (continued):
Sharing a sentence is not in itself a finding about the gene and the disease.
Allergy (continued). "Previous studies indicate that reduced activity of regulatory T cells, such as IL-10-producing Tr1 cells or Foxp3+ Treg cells is associated with allergic disease and that allergen-specific immunotherapy might increase their activity." (PMID 32391011, 2020). "We tested whether each discrete baseline confounder (sex, age, mode of delivery, breastfeeding, familial allergy) was associated to FoxP3 methylation independently of treatment by adding it to the fractional generalized linear models (GLM) as covariable." (PMID 30808949, 2019). "We considered that T-regulatory cells could be causative for the observed immune deviation, as in our allergy model acrolein led to an accumulation of atypical, anergic Foxp3+ cells in the murine spleen and the lungs." (PMID 28332605, 2017). "Similarly, it has been demonstrated that farm milk exposure in children has an allergy preventive effect which is linked to FoxP3 TSDR demethylation in peripheral blood cells." (PMID 27525046, 2016). "FoxP3 stable expression requires full CpG demethylation of its transcriptional regulatory regions, and, moreover, hypermethylation of the FoxP3 gene has been associated with reduced Treg function and allergy." (PMID 27525046, 2016). "Studies regarding DNA methylation changes in cytokine genes such as interferon gamma (IFN-γ), interleukin-4 (IL-4) and IL-5 and in Forkhead box P3 (FoxP3) indicate that changes in DNA methylation may predispose IgE-mediated food sensitization or allergy in early childhood." (PMID 36756279, 2023). "An imbalance of FOXP3+ Treg/Th17 cells may cause the onset of autoimmune and allergic diseases." (PMID 31572491, 2019). "Lower numbers of Helios-FoxP3+ Tregs, putative iTregs, in cord blood from children of allergic mothers may be another sign implying abnormal or delayed Treg development contributing to the increased risk of allergy development in these children." (PMID 30475891, 2018). "Thus, more studies are needed to evaluate the role of FOXP3 polymorphisms in allergic diseases." (PMID 27965764, 2015). "The effects of RosA on OVA challenge allergy in mice effectively improved the expression of anti‐inflammatory mediators, such as IL‐10 and forkhead box protein P3 (FOXP3)." (PMID 41523289, 2026). "If methylation in genes that control Treg function (e.g., FOXP3, IL-10, TGFβ1) increases, it can reduce gene activity, contributing to the development of allergies." (PMID 41176788, 2025). "Tregs, characterized by the expression of the transcription factor forkhead box p3 (Foxp3), provide critical defense against abnormal immune responses such as inflammation, infection, and allergy." (PMID 39125659, 2024). "A multigene and fate-reporter system demonstrated that the shift from Foxp3 Tregs to exFoxp3 (Th2) is IL-4-dependent during Heligmosomoides polygyrus infection and allergy." (PMID 39483462, 2024). "Studies have reported that SCFAs enhance Treg cell acetylation and promote Foxp3 stability, thereby suppressing Th2 overactivated immune responses in allergy." (PMID 39619969, 2024). "Down-regulation of miR-34a and miR-210 induces the expression of FOXP3, a major regulator that increases Tregs function, thus alleviating allergic diseases." (PMID 38572308, 2024). "They demonstrate that CD25+ FoxP3+ Tregs decrease in the group of individuals with rather extreme allergy." (PMID 38203472, 2023). "Coming back to our FOXP3 methylation picture, lower methylation levels were observed among infants with allergies, in contrast to the results of others." (PMID 37520545, 2023). "Previous studies have suggested that KAT5 contributes to chronic inflammatory responses, such as rheumatoid arthritis (RA) and allergy, by regulating the Foxp3 expression in regulatory T cells and STAT6 expression in B cells, respectively." (PMID 38110429, 2023). "Late allergic children (who develop allergy between the ages of 2 and 6 years) however had similar cord blood FoxP3/CD3γ mRNA ratios as healthy children." (PMID 36756279, 2023).
Allergy (continued). "The model was run for FOXP3, breastfeeding, use of antibiotic therapy up to the age of 2 years, other allergic diseases, and patients’ residence (city/village)." (PMID 36981683, 2023). "Moreover, it should be taken into account that these transcription factors, especially Stat5b, are directly involved in the correct expression of Foxp3, so that an alteration in their expression could also affect Foxp3 gene expression and, subsequently, susceptibility to allergic disease." (PMID 37334360, 2023). "The results showed that the level of FOXP3 was significantly dependent on breastfeeding, coexistence of allergic diseases, and the frequency of cleaning at home." (PMID 36981683, 2023). "This protein and peptide showed successful immune modulatory effects on T cell activation during autoimmune or allergic disease with an increase of Foxp3 expressing Treg cells." (PMID 37818377, 2023). "Tregs, characterized by the expression of transcription factor, forkhead box P3 (Foxp3), provide the critical defense against abnormal immune responses, such as allergy, inflammation, and infection." (PMID 35883204, 2022). "In contrast, the percentage of Foxp3+ Treg cells was significantly increased in the OIT group compared with the allergy groups and then significantly reduced compared with the OIT group when oral administration of allergen was stopped." (PMID 33299086, 2021). "This is the first demonstration of the implication of susceptibility genes to allergy in the development of KC, and this is the first time that the IL4 and FOXP3 genes association was analyzed with KC risk in an Algerian population." (PMID 34840678, 2021). "Foxp3 is essentially required for maintaining their immunosuppressive activity against infections, tumors, intestinal inflammation, allergy, and autoimmunity." (PMID 34440615, 2021). "Expression of allergy-associated cytokine genes, including Il4, Il5, Il9, Il13, and Il21, was higher in Nr4a-TKO cells, even when compared with Foxp3-KO cells." (PMID 33665581, 2021). "The allergy-protective action of probiotics mainly consists of regulation of innate immune system functions, Foxp3+ Tregs, immunoglobulin A, and intestinal epithelial permeability." (PMID 32283870, 2020). "It is known that Foxp3 and IL-10 play a key role in allergy suppression and maintaining immune tolerance." (PMID 33679699, 2020). "IL-4 activation of FoxP3+ Tregs influences their ability to maintain barrier immunity through their regulatory function of ILC2 activation during allergic disease." (PMID 32931477, 2020). "IL-4Rα signaling on Tregs modulates expansion and the functional stability of CD4+CD25+FoxP3+ Tregs in vivo during allergic disease." (PMID 32931477, 2020). "Consumption of raw cow milk during early infancy exhibited a preventive effect on the development of allergic diseases and increased the number of FoxP3 + Tregs." (PMID 30602375, 2019). "In allergic diseases, mannan-conjugated allergoids have been shown to increase allergen uptake and induce splenic Foxp3+Treg cell production." (PMID 30858392, 2019). "It was demonstrated that CD4+CD25+Foxp3+ natural Treg cells and inducible type 1 Treg cells inhibit the development of allergy via several pathways." (PMID 29921316, 2018). "The inhibition of allergic reactions is accompanied by increased numbers of CD4 (+) Foxp3 (+) T cells." (PMID 30459600, 2018). "Maternal rat milk in comparison with miRNA-deficient artificial formula increased mesenteric lymph node FoxP3 expression and decreased serum IgE levels to β-lactoglobulin in allergy-prone rat pups." (PMID 28933365, 2017). "Children who developed allergies in the first 3 years of life had lower numbers of CD4+CD25+FOXP3+ T cells and reduced FOXP3 expression and IL-10 production as newborns (P < 0.05)." (PMID 27646403, 2016). "There were fewer CD4+CD25+FOXP3+ T cells present in both the neonates with allergic mothers and the neonates who developed allergies in early childhood." (PMID 27646403, 2016).
Allergy (continued). "Overall, the risk factors for allergies in children of the present cohort included a reduced percentage of CD4+CD25+FOXP3+ T cells, reduced FOXP3 expression, and PPG-stimulated IL-10 secretion." (PMID 27646403, 2016). "We also included two soluble cytokine receptors (sIL4RA and sIL13RA2) and an exploratory component consisting of three allergy-related transcription factors (FOXP3, STAT3 and STAT6)." (PMID 26352148, 2015). "We have previously demonstrated that, at the moment of allergy diagnosis, patients with various clinical manifestations of allergy differed in the percentage of FoxP3 Tregs." (PMID 26457309, 2015). "Strategies to enhance the regulatory transcription factor FOXP3 have been used to treat or prevent allergic disease." (PMID 27965764, 2015). "Oral administration of L. plantarum NRIC0380 lyophilized powder was reported to suppress IgE production in β-lactoglobulin-immunized BALB/c mice and the induction of regulatory T cell (CD4+CD25+Foxp3+; Treg) was involved in the anti-allergy activity." (PMID 24936861, 2014). "To specifically address the role of Foxp3+ Treg in clinical manifestation of allergy, we used a model of passive systemic anaphylaxis (PSA), which reproduces the symptomatic phase of immediate-type hypersensitivity." (PMID 23922690, 2013). "Despite significant advances in this area, key aspects, such as in FoxP3+ Treg function in allergy, remain incompletely understood." (PMID 24086630, 2013). "Regulatory T cells (Treg) including constitutive and Ag-induced Foxp3+ Treg appear to be essential for controlling adaptive immunity and expression of autoimmune and allergic diseases." (PMID 23922690, 2013). "Regarding regulatory CD4+ T cells, the severity of allergic reactions has been associated with functional damage of allergen-specific Treg cells (CXCR5-FoxP3+IL-10+), Tr-1 (CXCR5-FoxP3-IL-10+) and, mainly in IgE-mediated disorders, TFR (CXCR5+FoxP3+IL-10+)." (PMID 37954580, 2023). "Our observations showed, however, that the level of FOXP3 was also influenced by the coexistence of other allergic diseases (at least one of the following: atopic dermatitis, food allergy, allergic rhinitis, or atopy), and the difference was statistically significant." (PMID 36981683, 2023). "The coexistence of allergic disease was associated with a lower level of FOXP3 (median = 32.70 vs. median = 58.60 in patients without other allergic diseases), p = 0.001." (PMID 36981683, 2023). "There is wide consensus on the crucial role played by forkhead box p3+ (Foxp3) Tregs to ensure immunological tolerance, while their dysfunctions may lead to allergic reactions, including FA." (PMID 35344298, 2022). "Further, the mutation in the human Foxp3 gene leads to a rare autoimmune dysregulation, polyendocrinopathy, enteropathy, X-linked (IPEX) syndrome along with other severe autoimmune diseases including arthritis, diabetes, allergy and IBD." (PMID 34440615, 2021). "Epicutaneous Viaskin application in a murine allergy model generated gut-homing LAP+Foxp3− Tregs that could suppress food-induced anaphylaxis." (PMID 33717186, 2021). "Although mono-colonization with both EcN-Ctrl and EcN-Chim reduced allergy in poly-sensitized mice, only the mono-colonization with EcN-Ctrl triggered the increased expression of IL-10 (P < 0.01), Foxp3 (P < 0.001), and IFNγ (P < 0.0001) mRNA in the lung as compared to GF poly-sensitized control." (PMID 33679699, 2020). "A high proportion of CD5+ B cells has previously been shown to be associated with subsequent allergy development, while a high proportion of CD4+ T cells having the FOXP3+CD25high phenotype is associated with a high risk of subsequent sensitization to common environmental allergens." (PMID 33007868, 2020). "Moreover, mice and humans with dysfunctional FoxP3 present with neonatal development of severe allergies characterized by hyper mucosal Th2 cells." (PMID 32931477, 2020).
Allergy (continued). "The balance between pro-inflammatory CD4+ Th2 cells and regulatory T cells, including CD4+Foxp3+ regulatory T cells (Treg) and CD4+Foxp3-, interleukin-10 (IL-10)-producing Type one regulatory T cells (Tr1) cells, is a significant determinant in the development of allergic disease." (PMID 31603425, 2019). "Recently, we hypothesized that milk transmits microRNAs (microRNA-155, microRNA-148a, microRNA-29b, microRNA-21) that may induce thymic FoxP3+ Treg differentiation thereby preventing the development of allergy." (PMID 27175277, 2016). "Our work implies that therapeutic modalities for treating autoimmune and inflammatory diseases, allergies and graft rejection should be designed to induce and/or expand FoxP3+Helios+ Tregs, while therapies against cancers or infectious diseases should avoid such expansion/induction." (PMID 26343373, 2015). "Interestingly, we observed that specific immunotherapy had stronger impact on the frequency of FoxP3 Tregs in peripheral blood in patients with more extensive allergic disease and lower level of Tregs at baseline." (PMID 26457309, 2015). "At present, there are no studies on the nucleocytoplasmic shuttling of Foxp3 and T-bet, key transcription factors associated with allergic diseases." (PMID 24733961, 2014). "Furthermore, we present strong evidence that indicate a central role for Treg (CD4+ CD25+ FoxP3+) in mediating allergy modulation in ocular allergy to hi-dose intraperitoneal sensitization." (PMID 24086630, 2013). "We thus next explored, whether a stronger importance of Foxp3+ Treg depletion during the allergen provocation phase could be observed in C57BL/6 mice, which are relatively less susceptible to allergy." (PMID 23071726, 2012). "As the significant role of Tregs (especially Foxp3+ Tregs) becomes evident in modulating allergic responses, new interest in the development of allergy treatments has been brought about by understanding the intricate mechanisms underlying tolerance towards allergens." (PMID 23071726, 2012). "As the results, we found that SAE immunotherapy reduced systemic allergy symptom scores, serum IL-4 levels, IL-4 and FcεR1α mRNA relative expression, and mast cell degranulation in ileum tissue in allergic mice while increasing Foxp3 and IL-10 mRNA relative expression." (PMID 39729447, 2024). "As well as inducing the Th2/TFH2/TFH13 axis, the severity of IgE-mediated allergies has been associated with functional impairment of non-follicular [Treg (CXR5-FoxP3+IL-10+) and Tr-1 (CXCR5-FoxP3-IL-10+)] and follicular [TFR (CXCR5+ FoxP3+IL-10+)] regulatory CD4+ T cells." (PMID 37954580, 2023). "Clostridium butyricum CGMCC0313 increases forkhead box P3 (FOXP3) Treg cells, TGF-β, and IL10, inverts the imbalance between Th1/Th2 and Th17/Treg cells, and reduces β-lactoglobulin-mediated intestinal anaphylaxis, thereby contributing to the reduction of the risk of allergy in mice." (PMID 33897683, 2021). "Unfortunately, we did not look at Treg numbers in our study, but since active suppression by Tregs is considered to be one of the main effector mechanisms for oral tolerance, the observed increase in histone acetylation of the FoxP3 gene might contribute to the allergy-protective effect." (PMID 31349704, 2019). "Foxp3, a crucial transcription factor for regulatory T cell function, participates in regulating the inflammatory immune response and could serve as a novel target candidate for the treatment of autoimmune and allergic diseases." (PMID 30823938, 2019). "In support of a protective role of n-3PUFA, it has been shown that DHA-induced suppression of allergic reactions was accompanied by increased forkhead box P3 (FoxP3)+CD4+ regulatory T cells, and intradermal injection of regulatory T cells could inhibit skin inflammation." (PMID 31518521, 2019).
Allergy (continued). "In mice, knocking-out the CNS1 results in a loss of peripheral tolerance with allergy and maternal-fetal conflict despite functional tTregs showing the importance of other control regions on FOXP3 and of non-tTreg FOXP3+ subsets to regulate the immune response." (PMID 26500760, 2015). "In addition, our data suggest that hi-dose sensitization may henceforth facilitate the further examination of CD4+ CD25+ FoxP3+ Treg in allergic disease." (PMID 24086630, 2013). "In this study, it was confirmed that a diet of Lp–FOS also alleviated soy protein-induced allergies by decreasing Th17 cells, as well as increasing the percentage of CD25+Foxp3+ Tregs in the spleen." (PMID 39796399, 2025). "Other cells actively participate in immune regulation during allergic diseases, such as dendritic cells, regulatory B cells (Bregs), and the recently discovered CD8+ regulatory cells (CD8+CD25+Foxp3+), and we will study these cells in our future work." (PMID 38106504, 2023). "L. acidophilus reduced the serum IL-6 and IL-17 levels and downregulated IL-17A expression, but upregulated CD25, Foxp3, and TGF-β expression in a murine model of allergy." (PMID 35216600, 2022). "Data in the literature showed that during eosinophilic and neutrophilic inflammations from CR-allergy, 30 and 10%, respectively, of the CD4+ T cells that infiltrated into lungs were FoxP3+, which is one of the signatures of potent immune suppression." (PMID 34135902, 2021). "Conversion of CD4+CD25+FOXP3+ T regulatory cells (Tregs) from the immature (CD45RA+) to mature (CD45RO+) phenotype has been shown during development and allergic reactions." (PMID 34072455, 2021). "Like in the lungs in the allergy model, a significant accumulation of CD3+ and Foxp3+ cells and a higher Foxp3/CD3 ratio was detected in tumors of mice treated with acrolein compared to sham-treated controls." (PMID 28332605, 2017). "Ingested probiotics are recognized by pattern recognition receptors, such as TLRs on DCs, that are essential for immunological homeostasis in the gut and that play an important role in allergic diseases; therefore, CD4+Foxp3+ Tregs are increased in MLNs." (PMID 27802847, 2016). "This study investigated the effect of DEX in CE-induced allergic reactions, especially the role of CD4 + CD25 + FOXP3+ Treg cells and some cytokines." (PMID 26968945, 2016). "In conclusion, CD25+Foxp3+ as well as Foxp3- and Foxp3+CD25-CD4+ Treg cells have been shown to be induced and to exert immunosuppressive effects after immunization with Ag-CTB in allergy experimental models." (PMID 22069660, 2010). "Another study on bile duct sclerosis suggested that IgG-associated CCL1 chemotaxis of Th2 and Foxp3+ Treg cells occurs via the CCL1/CCR8 pathway, although these studies did not focus on airways and allergies." (PMID 40051629, 2025). "Our study provides, for the first time, a clear demonstration of the absence of association of the allergy-associated IL4 and FOXP3 polymorphisms with KC in a sample from Western Algerian population." (PMID 34840678, 2021). "Furthermore, allergy immunotherapy inhibited the increasing of IL-25 and Th2 cytokines IL-4, IL-5 and IL-13 with induction of CD4+CD25+ Foxp3+ Treg cells." (PMID 29784924, 2018). "In addition, allergy immunotherapy led to a significant decrease in ER stress and PERK/CHOP signaling, increasing CD4+CD25+Foxp3+ Treg cells, and ameliorated airway hyper-responsiveness and airway inflammation." (PMID 29784924, 2018). "Indeed, in our models, we found an increase in the proportion of Foxp3+ CD4+ Tregs following OIT, which was similar to other reports employing different models of allergic disease; notably, this increase was markedly enhanced by OIT+kakkonto." (PMID 28107533, 2017).